ENSG00000204556 (zinc-finger pseudogene)
Gene: Transcribed unprocessed pseudogene on chromosome 20 (26,018,832 to 26,020,684, forward strand). Ensembl gene ENSG00000204556.
Diseases named in the same sentence as ENSG00000204556 in open-access papers:
ENSG00000204556 is named in the same sentence as 1 disease in open-access papers, as found by Europe PMC text mining. Sharing a sentence is not in itself a finding about the gene and the disease.
ENSG00000204556 shares sentences with these, for which no sentence is quoted: myopia (1 paper).